EGF (epidermal growth factor)
Diseases named in the same sentence as EGF in open-access papers (continued):
Sharing a sentence is not in itself a finding about the gene and the disease.
lung carcinoma (continued). "In addition, EGF-induced migration and invasion were suppressed by propolin C-treated A549 lung cancer cells." (PMID 29681982, 2018). "Furthermore, knockdown of NEDD4 inhibits EGF-dependent unconventional lysosomal cathepsin B secretion, which is an important cellular process for lung cancer cell migration." (PMID 29455656, 2018). "NEDD4 is required for the EGF-promoted lung cancer cell migration." (PMID 29455656, 2018). "EGF induced various rates of EGFR endocytic degradation in lung cancer cells." (PMID 29976202, 2018). "In addition, higher concentration of EGF in serum has been observed in lung cancer patients compared to healthy group." (PMID 29681982, 2018). "We explored here whether the expression of RBD-mutant p110α might affect the activation of RAC1, as measured by guanosine triphosphate (GTP) loading, upon EGF stimulation in EGFR-mutant human lung cancer cell lines." (PMID 30590030, 2018). "Moreover, CERK is involved in cell cycle progression induced by epidermal growth factor (EGF) in lung cancer cells via activation of ERK1/2." (PMID 29269995, 2017). "Next, we examined whether EGFR signaling regulates miR-1 expression over time in lung cancer cells treated with EGF or EGFR inhibitor." (PMID 28537886, 2017). "Finally, another study using A549 lung cancer cells, sulfhydryl-activated EGF conjugation with lipidic nanoparticles were colocalized with the labeled EGF receptors and the internalization of EGF-conjugated nanoparticles was visible." (PMID 27788212, 2016). "It was described as an epidermal growth factor signaling-regulated miRNA which can negatively regulate human lung cancer cell migration and invasion in vitro, is frequently down-regulated in lung cancer, and seems to play a role in enhancing in vitro cell migration and invasion in NSCLC." (PMID 26728044, 2016). "We concluded that a block of EGF/ERK signaling may inhibit lung cancer metastasis via miR-622-mediated repression of the HIF-1α axis, which, as a consequence, precludes feedback inhibition of miR-622 level by HIF-1α." (PMID 26528854, 2015). "In particular, HGF is known to work in combination with EGF on lung cancer cells." (PMID 26310485, 2015). "Furthermore, the medicine is also shown to inhibit the migratory effect induced by a combination of HGF and EGF, an axis of evil in clinical lung cancer in which they work synergistically in stimulating the progression of lung cancers." (PMID 26310485, 2015). "Toward this end, we screened human GFs known to promote growth of lung cancer cells, ie, EGF, IGF-I and VEGF utilizing working concentrations of each GFs reported in the literature, and the doses of nicotine restoring proliferation of each type of lung cells under consideration." (PMID 25885699, 2015). "We therefore hypothesized that lung cancer cell aggressiveness could be rescued by upregulating EGF/AKT/ERK signaling to compensate for the miR-622-mediated downregulation of HIF-1α." (PMID 26528854, 2015). "Thus, combined use of MET tyrosine kinase inhibitor (TKI) and EGF TKI has been suggested to be a valid novel combination to overcome TGF TKI acquired resistance in lung cancer." (PMID 26310485, 2015). "Our study has shown that HGF and EGF had a profound effect on the migration of lung cancer cells." (PMID 26310485, 2015). "Overall, results showed that EGF conjugation to nanocarriers could effectively target the EGFR overexpressing lung cancers when administered by inhalation." (PMID 25266303, 2014). "Indeed, Vav1 was shown to be tyrosine phosphorylated following EGF stimulation of neuroblastoma, pancreatic and lung cancer cells." (PMID 25313137, 2014). "Therapeutic approaches against EGF or EGFR represent a promising direction for lung cancer therapy." (PMID 24849319, 2014).
lung carcinoma (continued). "The interplay between EGFR and AURKA provides an explanation for the difference in EGF dependency between EGFR-WT and EGFR-mutant cells and may provide a new therapeutic strategy for lung cancer patients carrying EGFR mutations." (PMID 23520446, 2013). "Since the identification of some alterations in the expression of both epidermal growth factor/epidermal growth factor receptor (EGF/EGFR) in lung cancer pathogenesis, several therapeutic targeting agents have been employed for the treatment of lung tumors overexpressing these molecules." (PMID 26317020, 2013). "For instance, changes in circulating levels of epidermal growth factor (EGF) and transforming growth factor beta 1 (TGFβ1), due to functional genetic variants, could influence the risk to develop prostate and lung cancer, respectively." (PMID 23233863, 2012). "To determine whether CARMA3 mediates EGF-stimulated NF-κB activation in lung cancer cells, we used H1299 and A549 cells." (PMID 22615840, 2012). "Abnormalities in EGF-EGFR signaling, such as mutations that render the EGFR hyperactive or cause overexpression of the wild-type receptor, have been found in a broad range of cancers, including carcinomas of the lung, breast, and colon." (PMID 17973573, 2007). "These symptoms were associated with the underlying lung cancer condition and not with CIMAvax-EGF." (PMID 38304035, 2023). "In addition, hyperglycemia and metabolic dysregulation in cancer cells may accelerate the proliferation of lung cancer cells through epidermal growth factor expression, the reversal of the Warburg effect, and the reactivation of oxidative phosphorylation." (PMID 35626156, 2022). "BV could inhibit epithelial-mesenchymal transition (EMT), increase the expression of vimentin, down-regulate the E-cadherin expression, and inhibit the recombination of F-actin related to the tumor metastasis in lung cancer A549, H1739 and H23 cells induced by epidermal growth factor (EGF)." (PMID 36238572, 2022). "Consequently, loss of ERRFI1 expression in human lung cancer cells showed no response to the activated EGF pathway." (PMID 33869036, 2021). "However, RPE suppressed the increased proliferation by EGF in lung cancer A549 cells." (PMID 33158043, 2020). "Moreover, the endocytosis of EGF-stimulated pEGFR was explored in human lung cancer cells." (PMID 35582586, 2019). "The presence of SP-D could be associated with a favorable prognosis in lung cancer where it has been demonstrated to downregulate the EGF signaling, and unfavorable prognosis in non-pulmonary sites such as gastric, breast, and ovarian cancers." (PMID 30127783, 2018). "In addition, MEF2B knockdown reduced EGF-induced DDIAS expression in lung cancer cells." (PMID 27660814, 2016). "Overall, results suggest that EGF surface-modified nanocarriers could be delivered to lungs via inhalation and controlled delivery of drugs in the lungs will greatly improve the therapeutic options in lung cancer therapy." (PMID 25266303, 2014). "We observed that the migratory ability of lung cancer cells, assessed using wound-healing and Transwell assays, was significantly reduced in PYCR1-KO A549 and PYCR1-KO H1299 cells treated with EGF or TLR agonists compared with Ctrl cells." (PMID 41254241, 2025). "Stimulation by serum and epidermal growth factor induces trans-activation of NR4A1 in H460 and Calu-6 lung cancer cells, and high expression of NR4A1 promotes cell cycle progression, exerting a positive effect on mitosis in lung cancer cells." (PMID 40666103, 2025). "Moreover, the comparison with other cancers like cervical squamous cell carcinoma, colon cancer, and lung cancer suggests that these methylation patterns may be specific to BRCA, pointing to a potential mechanism underlying the upregulation of CCL18 and EGF in breast tumorigenesis." (PMID 40692603, 2025).
lung carcinoma (continued). "Cetuximab, an antibody specific for the epidermal growth factor (EGF) receptor, was administered to A549 lung cancer cells in comparison with the natural ligand EGF." (PMID 40075706, 2025). "Previous studies have demonstrated that nicotine stimulates epidermal growth factor (EGF) secretion and results in EGFR expression to induce the tumorigenesis of lung cancer." (PMID 37692503, 2024). "At the same time, cell therapy with rCD8+ T-cells of the spleen has an inhibitory effect on lung cancer cells and CSCs expressing Sox2 and markers Axl, CD117, EGF, PD-L1 and PD-1." (PMID 38664641, 2024). "In this study, we focus on four proteins that play crucial roles in the context of lung cancer: human cyclin-dependent kinase-2 (CDK2), SRC-2 domains of C-ABL, epidermal growth factor (EGF), and insulin-like growth factor-1 receptor kinase (IGF-1R)." (PMID 38905286, 2024). "Hypomethylation of EGF and EGFR leads to increased expression levels of these genes, presumably leading to higher activity of this vital pathway and driving lung cancer development." (PMID 39036344, 2024). "In some studies, nanoparticles have been modified with growth factors, such as the epidermal growth factor (EGF), which is overexpressed in cancer cells like lung carcinoma cells." (PMID 40066116, 2024). "In summary, zanidatamab mediates ligand-independent and EGF-driven growth inhibition in several HER2-expressing cell lines including breast, gastric, esophageal and lung cancer." (PMID 36914633, 2023). "A set of genes involved in epithelial cell growth (ERBB2, EGF, and FGF2) and Plasminogen (PLG) were connected to Cancer and Lung cancer in the Year 2 SPP1 network." (PMID 37513116, 2023). "BaP additionally promotes the expression of growth factors and their receptors, such as the epidermal growth factor (EGF) and EGF receptor (EGFR), the major contributors to lung cancer development." (PMID 37631277, 2023). "To exemplify how the PCN can be used to discover novel signaling responses, we considered pathway interactions with the EGF/EGFR signaling pathway, which has a well-established role in lung cancer." (PMID 36996232, 2023). "THC also inhibited EGF-induced growth by preventing the EGF-induced phosphorylation of ERK1/2, JNK1/2 and AKT in human lung cancer cell lines." (PMID 37946285, 2023). "Although MIG6’s role in shielding EGF–induced mutant EGFR internalization remains debated, its undisputed function in preserving EGFR stability in lung cancer cells is evident." (PMID 37834326, 2023). "Lung cancer cellular models have been used to evaluate the activity of Avns on tumor growth, migration, EMT, and anoikis induced by EGF." (PMID 35955669, 2022). "Studies have shown that in lung cancer, the saliac acid sites (N32, N151, and N389) of EGFR are usually close to the surface-binding sites of EGF." (PMID 36092699, 2022). "In lung cancer cells, MBQ-168 is more effective than MBQ-167 or EHop-097 at reducing ruffle formation in response to EGF." (PMID 36861094, 2022). "Assiddiq and coworkers used multiple reaction monitoring (MRM) in the H838 lung cancer cell line to study the effect of gefitinib on the phospho-sites of the EGFR protein before and after EGF treatment." (PMID 35563452, 2022). "In lung cancers, different CSC populations have been identified according to the expression of some markers, such as CD44, CD90, CD117, EGF, Axl, and Sox2, in different combinations." (PMID 36555420, 2022). "In other forms of lung cancer, we showed a heterogeneity of blood CTCs and CSCs populations, as well as changes in other cell populations (ALDH+, CD87+CD276+, and EGF+Axl+) in smokers." (PMID 36142766, 2022). "The cultured lung cancer cells were first preincubated with ETTE nanoprobes in PBS, then exposed to EGF to activate the EGFR signaling pathway." (PMID 35105871, 2022).
lung carcinoma (continued). "In human non-small cell lung cancer A549 and SW-1573 cell lines, THC, via CB receptors, inhibited EGF-induced growth, chemotaxis, and chemoinvasion; moreover, THC inhibited lung cancer growth and metastasis in vivo murine model." (PMID 33916164, 2021). "Contrary to these studies, other groups reported that IL-17RD overexpression potentiates epidermal growth factor (EGF)-stimulated ERK1/2 activation in 293 cells and steady-state ERK1/2 phosphorylation in mesenchymal lung cancer cells." (PMID 33833999, 2021). "For example, an interaction between FGFR1 and EGFR can marginally increase epidermal growth factor (EGF)-mediated AKT and STAT3 signaling outputs in lung cancer cells." (PMID 34068954, 2021). "Lung cancer CL1 and A549 cells stably transfected with α1,3-Fuc-transferases FUT4 or FUT6 showed reduced EGFR dimerization and phosphorylation upon EGF induction." (PMID 34069424, 2021). "THC reduced the EGF-induced phosphorylation of ERK1/2, JNK1/2, and AKT, responsible for the reduced migration and invasion observed in lung cancer cells." (PMID 33916164, 2021). "For instance, in the lung cancer cell lines H322 and the pancreatic cancer cell lines HPAF-II, EGF and TGFβ cooperated in the induction of EMT." (PMID 33777943, 2021). "Arsenic exposure in lung cancer cells reportedly upregulates expression of the EGFR ligand, heparin binding-EGF (HB-EGF) and activates EGFR phosphorylation (p-EGFR at Tyr 1173)." (PMID 32695675, 2020). "Converse evidence suggests that TRAF4, but not Skp2, is required for AKT K63 ubiquitination and promotes EGF-induced AKT membrane recruitment in human lung cancer cells to induce tumorigenic properties, but TRAF6 is unnecessary for EGF-induced AKT activation." (PMID 31988639, 2020). "Our data identify a novel Cx43/EGF/ERK1/2/FAK/RhoA/Rac1-dependent signaling axis, which determines the efficiency of lung cancer cell diapedesis." (PMID 30274176, 2018). "NEDD4 was co-immunoprecipitated with EGFR upon EGF stimulation in both A549 and H358 cells, suggesting that NEDD4 specifically interacts with activated EGFR in lung cancer cells." (PMID 29455656, 2018). "Inhibition of cell migration and invasion by propolin C was through the inhibition of EGF/EGFR-mediated signaling pathway, followed by EMT suppression in lung cancer." (PMID 29681982, 2018). "Increased ERK1/2 phosphorylation levels observed during A549 diapedesis and impairment of this process by chemical ERK1/2 inhibition reveals a novel intercellular Cx43/EGF/ERK1/2-dependent signaling axis, which is crucial for lung cancers’ diapedesis." (PMID 30274176, 2018). "EGF-induced PI3K/Akt and ERK activation was inhibited in propolin C-repressed EMT in EGFR wild-type lung cancer cells." (PMID 29681982, 2018). "We detected the phosphorylation of STAT3, ERK, AKT and FAK in lung cancer cells expressing either wild type BMX or BMXΔN and control cells followed by EGF stimulation." (PMID 28422715, 2017). "For example, enforced expression of IQGAP3 accelerated the migration and invasion of lung cancer cells by interacting with ERK1 and promoting EGF-induced activation of ERK." (PMID 28810875, 2017). "For instance, epidermal growth factor (EGF)/epidermal growth factor receptor (EGFR) has been reported to be responsible for elevated claudin-2 expression in CRC and lung cancer." (PMID 28383479, 2017). "Consistent with this, we found that EGF stimulation increases CDCP1 expression and EGFR inhibitor reduces the level of CDCP1 in lung cancer cells." (PMID 28537886, 2017).
lung carcinoma (continued). "DOR and MOR are overexpressed in lung cancer, and the overexpression of MOR enhances cancer progression by regulating Epidermal Growth Factor (EGF)-induced signalling events and epithelial mesenchymal transition (EMT) events." (PMID 28821282, 2017). "Our results showed that APRIL expression was under the control of EGF and BDNF signaling in NSCLC cells, meaning that these two factors are critical inducers of APRIL in lung cancer cells." (PMID 29312608, 2017). "A classification rule based on EGF, sCD26, Calprotectin and CEA was established, able to reasonably discriminate lung cancer with 97% sensitivity and 43% specificity in the training set, and 91.7% sensitivity and 45.4% specificity in the validation set." (PMID 28117344, 2017). "EGF treatment in vitro represents Kras4bG12D and EGFRL858R-induced signaling in vivo in lung cancer mice." (PMID 26956044, 2016). "In the current study, we have exploited the interconnected relationship between the EGF/EGFR axis with the induction of EMT20 and the ability of erlotinib to modulate the phenotype of lung cancer cell lines towards a more epithelial one." (PMID 27685624, 2016). "FTY720 has been shown to increase the cisplatin sensitivity of lung cancer cell through the activation of PP2A49 and enhance cell death in combination with cisplatin by inhibiting the Akt and epidermal growth factor (EGF) pathways in melanoma cells." (PMID 27160553, 2016). "For instance, the synergistic effect of Twist1 and the EGF/RAS pathway promotes tumor initiation and development in breast and lung cancer models." (PMID 26360779, 2015). "YZXJ has a significant role in reducing the migration, invasion and in vivo tumour growth of lung cancer and acts to inhibit the migratory and invasive effects induced by HGF and indeed by HGF/EGF." (PMID 26310485, 2015). "ID1 exerts its function by acting as dominant negative transcriptional repressors of bHLH factors; we found that ID1 is up regulated in response to nicotine and EGF via nAChR and EGFR in various lung cancer cell lines." (PMID 25028095, 2014). "Vav proteins are tyrosine phosphorylated in vitro by Syk, Lyn and Fyn and in response to EGF and PDGF stimulation in NIH3T3 fibroblasts and pancreatic and lung cancer." (PMID 25313137, 2014). "In this work, we developed a simple but effective microfluidic device to investigate the role of EGF, GM6001 in invadopodia formation in the process of invasion for A549 lung cancer cell line in an in vivo-like 3D microenvironment." (PMID 23441195, 2013). "In this work, we successfully developed a simple but effective microfluidic device to investigate the role of EGF, GM6001 in invadopodia formation in the process of lung cancer cell invasion in an in vivo-like 3D microenvironment." (PMID 23441195, 2013). "Numerous downstream molecular pathways, such as EGF/RAS/RAF/MEK/ERK and PI3K/AKT/mTOR are identified as having a key role in the pathogenesis of various forms of human cancer, including lung cancer." (PMID 24281308, 2012). "Down-regulation of endogenous XB130 with small interfering RNA (siRNA) reduced c-Src activity, IL-8 production, epidermal growth factor (EGF)-induced phosphorylation of Akt and GSK3β in human lung cancer A549 cells." (PMID 21884627, 2011). "In other studies, under the stimulation with epidermal growth factor (EGF), AHCYL1 expression is enhanced to maintain the expression of the NBCn1 transporter machinery in the plasma membrane, which plays a positive role in the migration of lung cancer cells." (PMID 40365293, 2025). "Currently, there have been no studies on the EGF gene rs1897990 and rs1524106 loci in young lung cancer populations domestically or internationally." (PMID 40696566, 2025). "First, YAP/TAZ depletion reduced EGF‐induced pY1068 phosphorylation in lung cancer cells experiencing a stiff matrix, which was not rescued by sAgrin supplemented matrix." (PMID 40165020, 2025).